FSHR (follicle stimulating hormone receptor)
Diseases named in the same sentence as FSHR in open-access papers (continued):
Sharing a sentence is not in itself a finding about the gene and the disease.
tumor (continued). "The favorable characters of [68Ga] Ga-NOTA-MAL-FSH1 such as convenient synthesis and specific tumor uptake warrant its further investigation for FSHR expression imaging." (PMID 29097913, 2017). "Their in vitro and in vivo studies showed that this drug displays higher anti-tumor efficacy against FSHR-expressing tumors with less cytotoxicity." (PMID 27139372, 2016). "In light of our findings, more studies are definitely needed to validate the recently discovered extragonadal FSHR expression and function, especially in the endothelial cells of different vascular vessel types in normal and tumor tissues." (PMID 27848975, 2016). "The blood vessels that expressed FSHR were located in a layer that extended 2 mm into and 5 mm outside of the tumor." (PMID 25652007, 2015). "We have finally compared the FSHR expression with the tumor grade and size, age of patients, and with the receptor status of ER, PR, and HER2." (PMID 25652007, 2015). "We show for the first time that, in contrast to tumor core vasculature which is disorganized and tortuous, the peripheral tumor FSHR+ blood microvessels are arranged in a hierarchical pattern: arterioles - capillaries - venules." (PMID 25652007, 2015). "In recent studies FSHR has been reported to play a role in immunotherapy of OC and tumor angiogenesis." (PMID 26779384, 2015). "Significant positive correlation was found between the density of peritumoral FSHR+ blood vessel and tumor size." (PMID 25652007, 2015). "There are many data concerning other tumours indicating the relationship of ectopic FSHR expression and malignancy grade." (PMID 25685198, 2015). "Second, the FSHR is preferentially expressed on the vasculature in the periphery of the tumor, thus defining the tumor boundary and potentially residual and recurrent disease after surgery or therapy." (PMID 26779384, 2015). "The percentage of blood vessels expressing FSHR reached a maximum of 100% at the demarcation line between the tumor and the normal tissue." (PMID 25652007, 2015). "In one tumor with MNA and its associated cell line, a few novel amplicons were found, which encompassed genes such as GDF7, FSHR, PRKCE, and TMEM18." (PMID 23656755, 2013). "Relative to normal mammary tissue, CMTs exhibited statistically significant downregulation of both LHR and FSHR transcripts and corresponding proteins (p < 0.01), with expression progressively decreasing as tumor malignancy increased, and with grade 3 tumors showing almost undetectable levels." (PMID 40431589, 2025). "Several cancers and their tumor vessel endothelial cells have been shown to express FSHR." (PMID 40490708, 2025). "We hypothesized that FSHR-positive tumor cells or endothelial cells of tumor vessels could be targeted and destroyed by the Phor21 lytic peptide fused to a selected fragment of the FSHβ ligand." (PMID 40490708, 2025). "We were unable to detect previously reported FSHR expression in tumor vessel endothelial cells, which may need further evaluation." (PMID 40490708, 2025). "In tumor vessel endothelial cells, FSHR may serve as a potential cellular tumor marker and novel target for cancer therapy." (PMID 40490708, 2025). "Since oophorectomy is a standard treatment for ovarian carcinomas, targeting FSHR should not cause on-target, off-tumor toxicity in healthy tissues in patients with OC." (PMID 37274261, 2023). "The functions of FSHR vary between epithelial cells and endothelial cells in tumor blood vessels." (PMID 37568488, 2023). "To further explore whether D2AP11 detects FSHR+ tumor cells in immunohistochemistry, we generated solid tumors in NSG immunodeficient mice." (PMID 36509287, 2022). "The major confounding issue is expression of FSHR in tumor samples from multiple organs." (PMID 34717708, 2021). "FSHR expression was observed in cancer cells, tumor associated stroma and blood vessels, whilst focal LHCGR expression was present predominately in the tumor cells." (PMID 33374698, 2020).
tumor (continued). "What is more FSHR might participate in tumor vascular network remodeling, as tumors are surrounded an organized microvessels distribution contrary to an heterogenous vascular network in normal tissue." (PMID 33329391, 2020). "Antihuman FSHR antibody, conjugated with tTF, binds the FSHR, which is abundant in peritumoral endothelium, initiating blood clotting with subsequent blood supply disruption and tumor necrosis." (PMID 30941099, 2019). "Since FSHR is a common marker of peritumoral vessels, a single therapeutic agent may, in principle, be applicable to a wide range of tumor entities." (PMID 31548530, 2017). "The blocking study suggested that the tumor uptake of the tracer was specific to FSHR." (PMID 29097913, 2017). "Interestingly, compared to tumor stroma, the FSHR signal was stronger in vessels of peripheral stroma." (PMID 31548530, 2017). "Combining FSHR-target therapy with anti-proliferative anti-tumor therapies and/or angiogenesis inhibitors may lead to additive or synergistic activity in malignant tumors." (PMID 31548530, 2017). "With regard to tumor vessel cells (primary and metastatic), it was suggested that FSHR might serve as a potential cellular marker of different tumors and provide a novel approach for targeted cancer therapy." (PMID 27848975, 2016). "FSHR+ blood vessels within these tumor zones were similar in caliber and structural components to FSHR-negative breast vessels associated with the normal-appearing tissue located at a distance greater than 10 mm outside the tumors." (PMID 25652007, 2015). "Moreover, we also observed the positive immunostaining with anti-FSHR antibody in tumoral cells of the investigated tumours." (PMID 25685198, 2015). "FSHR was shown to be expressed selectively on the luminal surface of tumor blood vessels." (PMID 25652007, 2015). "FSHR was reported to stain vessels located only at tumour border." (PMID 24073397, 2013). "This study investigated LHR and FSHR expression in 79 CMTs and 14 normal mammary tissues collected from 59 female dogs (ethical approval AW82903202-2-3), using immunohistochemistry (IHC) and quantitative real-time PCR, specifically examining their association with tumor malignancy and spay status." (PMID 40431589, 2025). "Moreover, researchers have engineered NKCE to simultaneously engage NK cells through Siglec-7 and OC targets through FSHR, which is specific to its target cells and is potent in killing tumor cells, as evaluated using a panel of different human ovarian tumor cell lines." (PMID 39741875, 2024). "FSHR-positive vessels could be the result of the tumoral neo-angiogenesis process, as demonstrated by their presence in the normal tissue immediately adjacent to the tumor." (PMID 37375761, 2023). "However, divergent immunohistochemical (IHC) findings have been reported for FSHR expression in tumor tissues, which could be due to the specificity of the antibodies used." (PMID 31548530, 2017). "Therefore, treatments targeting the tumor peripheral vessels, as those expressing FSHR, may be logically more likely to produce a cure compared to those targeting pathologically defective tumor core vessels." (PMID 25652007, 2015). "Together, these results suggested that FSH influences tumor metastasis, and small molecule targeted therapy of FSH/FSHR holds promise as a safe and effective approach for treating cancer metastasis." (PMID 38505602, 2024). "In human granulosa-like tumor cells (KGN), the direct effects of adiponectin on the mRNA expressions of CYP19A1 (aromatase) and FSHR were investigated." (PMID 37109523, 2023). "In contrast, patients that exhibited both high FSHR and high LHCGR tumor scores had the best survival outcome." (PMID 33374698, 2020). "A number of studies have shown the expression of FSHR in different types of tumor cells suggesting a potential role of FSH in tumorigenesis and suggesting FSHR as a potential target for cancer therapy." (PMID 30778333, 2019).
tumor (continued). "BSYX led a decrease in the tumor cell viability and cell migration ability and changed the expression levels of p-AKT/Akt, FSHR, Gankyrin and cyclinD1 and proteins HIF-α which were in line with those in vivo." (PMID 30402135, 2018). "Our results found that BSYX induced an increase in the expression levels of FSHR, Akt/p-Akt, Gankyrin, and cyclin D1 proteins and a decrease in HIF-α in mice tumor." (PMID 30402135, 2018). "The endothelial FSHR expression correlated significantly with the peritumoral CD34+ vessels’ density (p < 0.001) and tumor size (p = 0.01)." (PMID 25652007, 2015). "Our results indicate, for the first time, changes in wall structure and diameter of tumor peripheral blood vessels (vascular remodeling), a cellular process in which the endothelial FSH/FSHR signaling should play an important role." (PMID 25652007, 2015). "Furthermore, compared to tumor tissues, normal mammary tissues had dramatically higher expression levels of LHR and FSHR (p < 0.001 and p < 0.001, respectively)." (PMID 40431589, 2025). "Based on this, we hypothesize that differential expression of LHR and FSHR exists in CMT tissues, with expression levels correlating with tumor malignancy and spay status." (PMID 40431589, 2025). "In light of current knowledge, it is not clear which FSHR isoform plays a key role in the development and progression of neoplasms." (PMID 37568488, 2023). "This is the reason why tumor cells express FSHR and Fshr expression is not detected in the corresponding normal tissue." (PMID 34717708, 2021). "However, patients that exhibited both low FSHR and LHCGR tumor IR scores had the poorest survival outcome." (PMID 33374698, 2020). "In TUVECs, FSHR mediated the FSH transport, tumor angiogenesis and vascular remodeling." (PMID 30778333, 2019). "The FSHR specificity of [68Ga] Ga-NOTA-MAL-FSH1 was also confirmed by effective tumor uptake inhibition in the presence of excess FSH1 in both noninvasive PET imaging and biodistribution studies." (PMID 29097913, 2017). "No specific staining for VEGFR2 protein was observed in tumor vessels, including the peripheral FSHR+ blood vessels." (PMID 25652007, 2015). "Non-neoplastic thyroid follicles (i.e. the follicles situated outside the tumour) do not show the immunostaining for FSHR." (PMID 25685198, 2015). "In CMTs, we observed dynamic expression patterns of LHR and FSHR: compared to healthy mammary tissues, both gene transcription and protein expression of LHR and FSHR were markedly downregulated in CMTs, with further reductions accompanying increased tumor malignancy and decreased differentiation." (PMID 40431589, 2025). "In contrast, mature somatic cells surrounding the tumor do not possess FSHR." (PMID 37568488, 2023). "In a xenograft orthotopic subcutaneous and peritoneal model of OC in immunocompetent mice, intraperitoneal administration of FSHR-targeted T cells demonstrated significant therapeutic response, even tumor rejection, and an increased survival without on-target, off-tumor toxicity." (PMID 37274261, 2023). "According to a study by Bhartiya, FSH acts primarily via alternatively spliced FSHR-3 rather than the canonical FSHR-1 on stem/progenitor cells, from which neoplasms may develop." (PMID 37568488, 2023). "The endothelial FSHR expression on blood vessels of tumor stroma and peripheral tumor stroma might be involved in vascular remodeling at tumor periphery, but the role of FSHR in this process is not clear." (PMID 31548530, 2017). "Hence, the current study aimed to analyze how GPER may interact with the FSHR/LHCGR system in EOC and whether the prognostic significance of GPER in EOC cases (n = 151) may be dependent on the FSHR/LHCGR immunophenotype of the tumor." (PMID 23951246, 2013). "Therefore, occlusion/collapse of FSHR-positive peritumoral connecting vessels may halt blood flow towards tumors, resulting in the death of tumor cells from lack of oxygen and nutriments." (PMID 31548530, 2017).
tumor (continued). "GPER was found to correlate with GnRs in tumor samples and more importantly to be a positive prognosticator in EOC patients characterized as LHCGR/FSHR negative." (PMID 23951246, 2013).
cancer (54 papers, 2012 to 2025). A tumor composed of atypical neoplastic, often pleomorphic cells that invade other tissues. "Various polymorphisms of FSHR have been associated with risks of different types of cancers." (PMID 35002517, 2022). "The study of FSHR in cancer may help identify treatment and diagnostic options to improve the management of patients with cancer, as the inhibition of FSHR overexpression may be beneficial in reducing the carcinogenic effect and progression of OC (especially EOC)." (PMID 39741875, 2024). "Therefore, we speculated that the FSHR Asn680Ser polymorphism is associated with cancer susceptibility." (PMID 39741875, 2024). "Several laboratories tried to trace the complex signaling pathways connecting FSH/FSHR to its ectopic expressions in various pathologies including cancer biology." (PMID 41024941, 2025). "Extragonadal follicle-stimulating hormone (FSH) receptor (FSHR) expression in various cancers and their endothelial vessel cells has highlighted novel opportunities for targeted FSHR therapy." (PMID 40490708, 2025). "Recombinant human FSH treatment significantly decreased the cytotoxicity of Phor21-FSHβ33-53 C/S conjugate in FSHR-positive cancer cells." (PMID 40490708, 2025). "Significant differences in LHR and FSHR expression were detected between grade 3 malignant tumors and benign mammary tumors (p < 0.01 and p < 0.05, respectively)." (PMID 40431589, 2025). "The fusion lytic peptide Phor 21 conjugated with the FSHβ chain 33–53 fragment (Phor21-FSHβ33-53 C/S) specifically targeted and destroyed cancer cells expressing FSHR." (PMID 40490708, 2025). "Phor21-FSHβ33-53 C/S (further addressed as Phor21-FSHβ) treatment in vivo significantly inhibited the growth of FSHR-positive cancer xenografts, resulting in necrosis." (PMID 40490708, 2025). "Schematic overview of the Phor21-FSHb33-53C/S (Phor21-FSHβ) conjugate or CTX specifically targeted to kill FSHR-positive cancer cells." (PMID 40490708, 2025). "Follicle-stimulating hormone receptor (FSHR), expressed in vascular endothelial cells of different malignancies, has recently been investigated as a potential pan-receptor for cancer therapy." (PMID 36874103, 2023). "Selective FSHR expression on the surface of blood vessels has been observed in various types of cancers." (PMID 37568488, 2023). "The actions of human FSH and its receptor (FSHR) and mutations therein have mainly been studied using in vivo models, primary cells, cancer cells and cell lines ectopically expressing the FSHR." (PMID 35471239, 2022). "Further studies are warranted for potential translational advancement of this tool for a variety of ovarian and other cancers expressing FSHR." (PMID 36509287, 2022). "Follicle stimulating hormone (FSH) and its receptor (FSHR) have been reported to be responsible for several physiological functions and cancers." (PMID 35002517, 2022). "FSH/FSHR has been identified in several cancer tissues and is supposed to play a role in angiogenesis." (PMID 34541367, 2021). "Published reports regarding FSHR expression on multiple extra-gonadal adult tissues and also on cancer cells affecting multiple organs has raised many eyebrows and we have recently addressed various concerns." (PMID 34717703, 2021). "FSHR are expressed on cancer cells which arise due to excessive and selective self-renewal of tissue-resident stem/progenitor cells whereas adjacent somatic, mature cells evidently remain negative for FSHR." (PMID 34717708, 2021). "Present review further addresses various concerns raised in recent times by the scientific community regarding extragonadal expression of FSHR, especially in cancers affecting multiple organs." (PMID 34717708, 2021). "From a rational point of study design, testing the specificity of FSHR antibodies using (transfected) cancer cell lines or extragonadal tissues cannot be considered sufficient." (PMID 30778333, 2019).